CXCL12 (C-X-C motif chemokine ligand 12)
Diseases named in the same sentence as CXCL12 in open-access papers (continued):
Sharing a sentence is not in itself a finding about the gene and the disease.
tumor (continued). "For example, tumor-associated macrophages (TAMs) have been shown to secrete the homeostatic chemokines, CXCL12 and CXCL13, which bind to their respective G protein-coupled receptors on malignant B cells, CXCR4 and CXCR5." (PMID 28424405, 2017). "Deletion of the JunD gene in the stroma promoted tumor growth and metastasis, associated with increased ROS production, with consequent accumulation of HIF1α and HIF1α-dependent induction of CXCL12, activating CXCR4, promoting CAF differentiation." (PMID 29137220, 2017). "CXCL12 is known to mediate normal cell migration and is implicated in many neoplasias, including the overexpression of its canonical receptor, CXCR4, in various cancers." (PMID 29250030, 2017). "CXCL12 has been extensively studied and shown to be released by CAFs causing premalignant activities in tumour cells and in the cells of the tumour milieu." (PMID 28987144, 2017). "Although CXCR4 is a membrane receptor, its intracellular segregation following CXCL12 stimulation has been widely reported and associated with high tumor malignancy." (PMID 28186979, 2017). "Several circulating cytokines, including hepatocyte growth factor (HGF), TGF-beta, CXCL8 and CXCL12, have been implicated as contributors to anoikis signaling in some kinds of tumor cells." (PMID 28430645, 2017). "Tumor-associated fibroblasts are critical component of tumor stroma that produce and secrete various tumor-promoting factors, including CXCL12 or stromal-derived factor 1 α (SDF1α)." (PMID 27590504, 2016). "It has been reported that cancer-associated fibroblasts can release CXCL12 at the primary tumor site to promote the primary tumor growth and invasion." (PMID 26993780, 2016). "We propose that NF-κB dependent tumor-associated inflammation co-participate in malignant progression concomitant to normal hematopoietic failure through disruption of CXCL12/CXCR4 and VLA4/VCAM-1 communication axes." (PMID 27594840, 2016). "The diagnostic specificity for CXCL12 levels (80%) was lower than that for classical tumor markers and CRP, similarly to positive predictive value (PPV)." (PMID 27041792, 2016). "In a co-implantation mouse xenograft model with MCF-7 and human fibroblasts, cancer-associated fibroblasts promoted tumor growth and angiogenesis by recruiting endothelial progenitor cells, mediated in part by SDF-1/CXCL12." (PMID 26828520, 2016). "The present study aimed to analyze two polymorphisms in FOXP3 and one polymorphism in CXCL12 in WT samples, in a search for new possible molecular markers to this childhood neoplasia." (PMID 27830498, 2016). "In conclusion, a positive CXCL12 expression is an independent risk factor for subsequent tumor recurrence, showing the highest hazard ratio compared with other pathological features." (PMID 27439769, 2016). "CXCR7 is overexpressed on tumor-associated vasculature as well as on subsets of cancer cells in the primary tumor environment, and this receptor has been shown to lower overall CXCL12 levels in tumors." (PMID 25909600, 2015). "Related to its role in angiogenesis, chemotaxis, and cell proliferation, CXCL12/CXCR4 signaling has also been linked to different pathologies including tumor progression and metastasis, as discussed in more detail later." (PMID 26347749, 2015). "AMD3100 attached to the NPs will also block CXCR4/CXCL12, reducing infiltration of tumor-associated macrophages, enhancing the anti-angiogenic effect." (PMID 27429863, 2015). "Nonetheless, caution in evaluating the associative results regarding both CXCR4 and CXCL12 expressions in the tumor microenvironment is highly recommended." (PMID 26161302, 2015). "To investigate the mechanism behind the spontaneous aggregation of fibroblast-like cells and LAM cells we examined the role of the CXCR4 / CXCL12 axis which is responsible for the recruitment of cancer associated fibroblasts in tumours." (PMID 25978616, 2015).
tumor (continued). "Breast cancer cells, with upregulated CXCR4 genes, have been found engrossed to CXCL12 expressing cells in the lymph nodes, liver, and lungs, thus causing metastasis of disconnected tumor cells." (PMID 25814785, 2015). "CXCR7 controls tumor diffusion through CXCL12 gradients and it is frequently detected in GBM-associated vasculature." (PMID 24904289, 2014). "Higher expressions of CXCR1, CXCR2, and CXCR4 with their ligands CXCL5, CXCL8, and CXCL12 appear to be associated with tumor angiogenesis, metastasis, and poor survival in NSCLCs." (PMID 25271023, 2014). "We have also performed a two-sided Pearson correlation analysis to determine if the relative expression of CXCR4, CXCR7 and CXCL12 in tumours is associated with the relative expression of COUP-TFI." (PMID 24906407, 2014). "Dysregulation of HIF and/or cytokines, such as the CXCR4/CXCR7/CXCL12 axis, is one probable cause of increased angiogenesis via the overexpression of tumor VEGF." (PMID 24629239, 2014). "Our data support this notion, as CTCE-9908-treated tumors showed enhanced necrotic areas, suggesting that loss of the CXCL12/CXCR4 axis mediated cell survival leading to enhanced necrosis in tumor cells." (PMID 24472670, 2014). "Tumor associated fibroblast (TAF) secreted CXCL-12 (SDF-1) was found to directly promote the growth of CXCR4 expressing tumors in vivo and in vitro." (PMID 23744479, 2013). "Production of the chemokine CXCL12, also known as stromal cell-derived factor 1 (SDF-1), by MSCs is required for their in vitro migration in response to tumor cells and has also been implicated in stimulation of tumor growth." (PMID 24064862, 2013). "In extensive studies of malignant neural and astrocytic tumors, we and others found increased CXCL12 expression in the endothelium of tumor-associated blood vessels." (PMID 22427929, 2012). "CXCL12/CXCR4 signaling has been reported to stimulate growth of several tumors including breast, with carcinoma-associated fibroblasts (CAFs) being an important source of CXCL12 in the tumor microenvironment." (PMID 22152016, 2011). "CXCR4 is expressed in malignant tumor cells whereas its ligand SDF-1 (CXCL12) is expressed mainly by cancer associated fibroblasts (CAF)." (PMID 19340288, 2009). "The CXCL12/CXCR4 axis is specifically implicated in tumor progression." (PMID 40433410, 2025). "In xenograft models, rosiglitazone treatment resulted in a marked reduction in tumor volume, decreased microvessel density, and increased expression of C-X-C motif chemokine ligand 12 (CXCL12), a signaling protein associated with lower malignancy and better survival." (PMID 40145087, 2025). "In breast cancer, CXCL12 is associated with tumor cell migration, invasion, and metastasis." (PMID 40486614, 2025). "Assessing tumor CXCL12 expression may help stratify patients based on their risk of disease progression and guide personalized treatment strategies." (PMID 40481962, 2025). "Hui and colleagues reported that miR-101, by targeting C-X-C chemokine receptor 7 (CXCR7), which is overexpressed in OSCC, prevents its binding to C-X-C chemokine ligand 12 (CXCL12) that is encoded by the CXCL12 gene, thus reducing cell adhesion, viability and tumor growth." (PMID 41209683, 2025). "Moreover, high tumor expression of CXCL12 has been associated with poor survival outcomes in CRC patients." (PMID 40943634, 2025). "Research has demonstrated that senescent CRC tumor cells inhibit the infiltration of CD8+ T cells by secreting elevated levels of chemokine ligand 12 (CXCL12), resulting in the loss of chemokine receptor (CXCR4) on T cells and impairing their directed migration." (PMID 40896432, 2025). "Tumor-associated lymphatic vessels control CD8+ T cell exit from tumors via the chemokine CXCL12." (PMID 41511312, 2025).
tumor (continued). "Our study establishes a Tumor Microenvironment-derived Prognostic Model (MPM) that integrates eight TME-associated genes (CXCL12, GZMB, ITPR2, LYN, RAB9B, RGMB, RUFY4, TRIM16) to stratify AML patients into distinct risk categories with significant survival differences." (PMID 40608798, 2025). "CXCR4+ CD8+ T cells exit tumors through CXCL12+ tumor-associated lymphatic vessels." (PMID 38786066, 2024). "Additionally, CXCR7, a receptor related to CXCR4 and CXCL12, has been associated with the growth and metastasis of tumor cells in colon cancer, melanoma, and BCa." (PMID 39070795, 2024). "CXCL12 secreted by tumour cells recruits immune cells, such as M2-type tumour-associated macrophages, T regulatory cells, and myeloid-derived suppressing cells, and guides them to produce specific immunosuppressive responses, which results in the promotion of tumour growth." (PMID 38594611, 2024). "Additionally, we found that levels of both PLP1 and RELN were significantly associated with levels of CXCL12, which plays an important role in numerous physiological and pathological processes, including tumour metastasis." (PMID 38307969, 2024). "Moreover, the expression of various CAF-associated cytokines, including IL-1, IL-6, IL-8, CCL5 and CXCL12, in ADSCs was significantly elevated after coincubation with sEV derived from tumor cells and ascites, as detected by RT–qPCR." (PMID 38233863, 2024). "Furthermore, the stimulation of the CXCR7 signaling pathway caused by CXCL12 increases the proliferation, invasion and metastasis of tumor cells." (PMID 37635248, 2023). "Notably, we also observed that the disruption of muscle tissue structure in grade 3 tumors is associated with a reduction in CXCL12‐positive areas within the tumor." (PMID 36300800, 2023). "Mice with USP15-deficient T cells were found to generate excessive IFN-γ, which up-regulated expression of PD-L1 and CXCL12, causing effector T-cell exhaustion alongside infiltration of Tregs and myeloid-derived suppressor cells (MDSCs) into tumours, which promoted tumour formation." (PMID 37503572, 2023). "Another chemokine, CXCL12, which can drive monocyte migration, could be induced by radiation therapy and trigger tumor-associated macrophage aggregation in tumor tissues." (PMID 37494663, 2023). "Although scarce, there are some recent reports associating CXCL12 with tumor-suppressing effects." (PMID 36725964, 2023). "The CXCL12 that is released from tumor cells or at the site of tissue damage can interact with CXCR4 on the mesenchymal stem cell membrane (MSCM) to cause MSCs to accumulate at tumor sites." (PMID 36756155, 2023). "Additionally, CMS4 tumors express chemokines such as CCL-2, CCL-5 and CXCL-12 that attract myeloid cells, leading to the infiltration of cancer-associated fibroblasts (CAFs), MDSCs and tumor-associated macrophages (TAMs)." (PMID 37511431, 2023). "Recent findings suggest that CXCL12 could serve as a novel marker for ECs specific to PCa, as its expression was markedly elevated in tumor-associated ECs in comparison to in vitro ECs." (PMID 37895416, 2023). "CXCR4 binds macrophage migration inhibitory factor (MIF), a factor implicated in the control of innate immunity, as well as CXCL12, a molecule well-known for its function in immunological surveillance, inflammatory response, tissue homeostasis, and tumor development and metastasis." (PMID 37190141, 2023). "It is reported that the CXCL12 gene polymorphism could contribute to CRC by mediating tumor angiogenesis, progression, metastasis and leukocyte migration." (PMID 35114976, 2022). "Hypoxia is another hallmark in GBM and causes an increase in HIF-1 expression, which boosts CXCL12 production in tumor cells, influences tumor cell spreading via CXCR4 receptor binding to endothelial cells, and stimulates the VEGF expression, resulting in enhanced angiogenesis." (PMID 35269652, 2022).
tumor (continued). "In addition, the enhanced survival of docetaxel-treated PCa cells was mainly mediated by CXCR4 activation from the increased secretion of CXCL12 from CSF-1-activated tumor-associated macrophages." (PMID 35406450, 2022). "CXCL12 can be expressed by tumor-associated fibroblast, macrophages, or endothelial cells." (PMID 36231109, 2022). "Similarly, lower expression of CXCR4/CXCR7 and CXCL12 is associated with increased tumor size, local invasion, poor differentiation, advanced lymph node stage, advanced tumor stage, and lymphovascular invasion." (PMID 35406582, 2022). "This may be attributed to the intracellular or membrane-bound localisation of CXCL12 observed in tumour-associated ECs." (PMID 35464424, 2022). "The etiology for CXCL12 expression not tracking with the expression of other CAR cell–associated markers is unclear, but literature in other tumor types suggests that loss of CXCL12 may confer a selective advantage." (PMID 35309866, 2022). "In the tumor microenvironment, PAI1 expression is upregulated in tumor-associated macrophages after being stimulated with cancer-associated fibroblasts-generating CXCL12 and promotes the malignant behavior of the HCC cells by mediating epithelial–mesenchymal transition." (PMID 35223517, 2022). "In addition, CXCR4 plays an important role in inflammation with its ligand CXCL12 and associates with pathological processes such as tumor proliferation, angiogenesis, and metastasis." (PMID 34804954, 2021). "Increased mRNA expression of ADAMTS1, CCL19, and CXCL12 was associated with peritoneal metastasis, suggesting that these genes related to the tumor microenvironment may play a significant role in tumor progression." (PMID 34830815, 2021). "Furthermore, the CXCL12/CXCR4 axis has been implicated in local tumor-supporting effects: experiments with NB cell lines and an orthotopic NB mouse model revealed a CXCL12-dependent beneficial effect of CXCR4 on tumor growth and -survival." (PMID 33287630, 2021). "It was shown that CXCL12 secretion could be induced in response to radiation therapy and cause accumulation of TAMs in the tumor." (PMID 33919517, 2021). "CXCL12 (SDF-1α)/CXCR4 signaling is upregulated in radiation-induced EndoMT in tumor vasculature where it is required for tumor-associated macrophage recruitment, and knockdown of either of CXCL12’s receptors, CXCR4 and CXCR7, disrupts angiogenic sprouting in vitro." (PMID 34692672, 2021). "In addition, CXCR4+ TAMs were found to migrate toward CXCL12-expressing perivascular cancer-associated fibroblasts, and once located on the blood vessel, TAMs became sessile and promoted tumor cell intravasation." (PMID 34884995, 2021). "In addition, CD26/DPP4 cleaves ligands CXCL10 and CXCL12, which play a role in lymphocyte migration and tumor immune surveillance, thus increasing susceptibility to metastasis." (PMID 34055551, 2021). "However, transcripts encoding cytokines Cxcl12 and Il33 had a significantly higher expression in the tumor-derived CAFs, suggesting a tumor microenvironment induced activation of these genes in this subpopulation." (PMID 32455670, 2020). "In addition, high expression of CXCL12 in the cytoplasm of tumor cells in the primary tumor was associated with better OS." (PMID 32188473, 2020). "POU class 5 homebox 1 (POU5F1) expression is associated with tumorigenesis (RefSeq: 5460), and C-X-C motif chemokine ligand 12 (CXCL12) encodes a protein that functions in many diverse cellular functions including tumor growth and metastasis (RefSeq: NG_016861.2)." (PMID 32649728, 2020). "As a consequence of CXCL12 release, tumor-associated CXCR4-expressing ECs proliferate." (PMID 32983169, 2020).
tumor (continued). "Similarly, CAFs were demonstrated as the major sources of chemokines, releasing CXCL12 to recruit monocytes as tumor-associated macrophages (TAMs) in tumor microenvironment." (PMID 33122682, 2020). "Our results suggest that CXCL12 expression in the primary tumor may improve risk stratification in patients with metastatic GCTs." (PMID 31412792, 2019). "Blocking of CXCL12 or CXCR4 could prevent the influx of tumor associated macrophages and myeloid suppressor cells which mediate re-vascularization and immunosuppression respectively." (PMID 30813533, 2019). "Furthermore, CXCL12 can be secreted in tumor microenvironment by carcinoma-associated fibroblasts and mesenchymal cancer stem cells." (PMID 31275385, 2019). "Thus, in vivo CXCL12 inhibition with NOX-A12 led to a tumor microenvironment less receptive for MM cells, causing reduced MM cell growth and disease progression." (PMID 30787933, 2019). "Indeed, the stable CXCL12 gene reexpression in MiaPaCa2 cancer cells, which is usually epigenetically silenced, caused a significant decrease in tumor growth and migration." (PMID 31275385, 2019). "Additionally, CXCL12/SDF1 secreted by tumor cells is associated with increased endothelial permeability, both locally and systemically." (PMID 31645420, 2019). "Here we identify for the first time a physiological source for CXCL12 in the TME- specifically from tumor-adjacent carcinoma associated fibroblasts, and reveal a unique role for the TME in directly influencing tumor cell motility through mDia formin-dependent cytoskeletal regulation." (PMID 29596520, 2018). "In addition, CXCL12 expressed by Tumor Associated Fibroblasts (TAF) and tumor cells has been demonstrated to play an important role in favoring tumor growth and progression in primary lesions." (PMID 30459756, 2018). "In addition, CXCL12 is expressed in the tumor microenvironment mainly by cancer-associated fibroblasts and has been indicated for resistance to checkpoint inhibitors such as anti-PD-L1 through T-cell exclusion." (PMID 29562664, 2018). "The expression of CXCR4 was mostly confined to the cytoplasmic membrane and cytoplasm of neoplastic cells whereas CXCL12 was mainly located to cytoplasm and, in a lesser extend to cytoplasmic membrane of tumor cells but also to tumor-associated macrophages and cancer-associated fibroblasts." (PMID 30012106, 2018). "In addition to its physiological role, CXCL12/CXCR4 signaling has been implicated in driving tumor cell proliferation, survival and migration in various solid tumors." (PMID 28055968, 2017). "As for the combination of CXCR4 and CXCL12 levels, CXCR4high/CXCL12high in GC is significantly associated with tumor invasion depth, LN involvement, and higher TNM stage, which causes the worst prognosis, whereas patients with CXCR4low/CXCL12low show the best prognosis." (PMID 28544785, 2017). "Above that, we could now demonstrate that CXCL12 positivity at primary tumor site was associated with a significant increased risk of lymph node recurrency associated death." (PMID 29348861, 2017). "Tumor-associated vasculature expresses endothelial CXCR7 that scavenges CXCL12." (PMID 29117251, 2017). "Thus, we draw that QRHX played a more important role in inhibiting tumor growth by regulating TAMs in mice, which was found to be associated with the inhibition of inflammation and the CXCL12/CXCR4/JAK2/STAT3 signaling pathway." (PMID 28630636, 2017). "Additionally, circulating CXCL12 levels have been associated with tumor angiogenesis in patients affected by multiple myeloma." (PMID 29240722, 2017). "Interestingly, recent studies have indicated the pivotal role of CXCL12/CXCR4 expression in tumor metastasis, showing that it is actively implicated in angiogenesis." (PMID 27668882, 2016). "Furthermore, CXCL12 production is triggered in hypoxic environments in tumor cells and is implicated in the promotion of tumor growth in mouse prostate tumors following overexpression of its receptor CXCR4." (PMID 27834814, 2016).